CLU (clusterin)
Diseases named in the same sentence as CLU in open-access papers (continued):
Sharing a sentence is not in itself a finding about the gene and the disease.
hepatocellular carcinoma (31 papers, 2007 to 2026). A malignant tumor that arises from hepatocytes. "Known to be involved in the clearance of cellular debris and apoptosis, CLU is an extracellular chaperone associated with tumor progression in multiple malignancies such as bladder, colon, hepatocellular carcinoma and renal cell carcinoma, and resistance to radiotherapy." (PMID 39194522, 2024). "It was observed that the serum levels of CLU were elavated in the hepatocellular carcinoma group compared to the liver cirrhosis group, suggesting an involvement of CLU in the process of carcinogenesis." (PMID 37685987, 2023). "Increased expression of CLU has been demonstrated in the metastatic or cancerous cells of colon, bladder, and hepatocellular carcinoma." (PMID 36071866, 2022). "CLU can be detected in the serum of the patients with early stage CRC or hepatocellular carcinoma, and its expression gradually increases during CRC progression." (PMID 36267311, 2022). "In hepatocellular carcinoma cells, CLU silencing leads to a reduction in Smad3 phosphorylation in concomitance with the inhibition of EMT markers." (PMID 34360868, 2021). "On the other hand, a decreased serum clusterin level has been proven during osteoarthritis, systemic lupus erythematosus, sepsis, human hepatocellular carcinoma, and esophageal squamous cell carcinoma." (PMID 31940868, 2020). "CLU increased MMP-2 expression in hepatocellular carcinoma cells, while CLU overexpression inhibited MMP-9 expression by reducing NF-κB activation in vascular smooth muscle cells." (PMID 31885575, 2019). "Clusterin is a secretory protein and its expression is increased in various disease conditions such as cholestasis, liver fibrosis, hepatocellular carcinoma and renal fibrosis." (PMID 31739636, 2019). "GRP78 also promotes CLU to cytoprotect cancerous cells in hepatocellular carcinoma (HCC)." (PMID 37685987, 2023). "Finally, thyroid hormones also downregulate CLU expression in human hepatocellular carcinoma cells after treatment by thyroid hormones." (PMID 37685987, 2023). "Recent studies have shown that the changes in the patterns of glycosylation on hemopexin and clusterin may be useful for the diagnosis for hepatocellular carcinoma." (PMID 22672759, 2012). "Also, interleukin-6 induced CLU expression in hepatoma cells (HepG2) whereas CLU was down-regulated in rat glial cultures exposed to the same cytokine." (PMID 17634137, 2007). "This may be explained by a high secretion rate of CLU, which would keep the intracellular pool of mature CLU protein low, and has been observed to occur rapidly in human liver carcinoma cells (HepG2) with half-times of 30–35 min." (PMID 17634137, 2007). "Consistent findings across diverse cell types, including cancer cells, retinal pigment epithelial cells, hepatocellular carcinoma cell lines, and endothelial tumor cells, emphasize the role of histone hyperacetylation induced by histone deacetylase inhibition in promoting CLU expression." (PMID 38667280, 2024). "Therefore, further to the research indicating the involvement of clusterin in the regulation of the Akt pathway and oxaliplatin response in hepatocellular carcinoma (HCC), we conducted experiments to demonstrate the correlation between clusterin and oxaliplatin resistance." (PMID 38067236, 2023). "In vitro studies conducted in breast, renal, nasopharyngeal, and hepatocellular cancer cell lines found that MMP-9 and MMP-2 expression is reduced following CLU silencing, concomitantly with a decrease in cell motility and invasion." (PMID 34360868, 2021). "Clusterin plays an important role in the diagnosis and prognosis of various liver diseases, such as biliary atresia and hepatocellular carcinoma, and differentiation between liver and non-liver cancers." (PMID 40089787, 2025). "In hepatocellular carcinoma, it is not clear whether clusterin silencing inhibits the invasion and metastasis of this disease." (PMID 22949882, 2012).
hepatocellular carcinoma (continued). "This aligns with the finding that silencing CLU gene transcription decreases the phosphorylation level of AKT and GSK-3β, subsequently inhibiting the proliferation of HCCLM3 cells in hepatocellular carcinoma (HCC)." (PMID 38667280, 2024).
amyloid (29 papers, 2012 to 2025). "There is a relationship between CLU (clusterin (apolipoprotein J)) and Aβ in vivo through the utilization of a model organism of amyloidosis with a CLU deficiency." (PMID 36291661, 2022). "Clusterin, known to interact and mediate the clearance of Aβ, and Vitronectin have both already been associated with various subtypes of amyloidosis." (PMID 35008745, 2021). "Taken together, these data show that partial yet physiological reduction of CLU expression increases severity of amyloid pathology and exacerbates amyloid-associated neurotoxicity and gliosis." (PMID 33246484, 2020). "It is noteworthy that non‐amyloidosis‐associated proteins reported in human cases of AApoAIV amyloidosis such as vitronectin, serum albumin, clusterin, collagen alpha‐2 (I) chain, collagen alpha‐1 (I) chain, and actin 48 were also found in our samples." (PMID 29774542, 2018). "Since abundant gliosis is associated with the presence of amyloid pathology, we next assessed whether CLU overexpression had a differential effect on inflammatory changes in APP/PS1 mice." (PMID 33246484, 2020). "CLU overexpression also ameliorated amyloid-associated neurotoxicity and gliosis." (PMID 33246484, 2020). "A role for CLU that affects basolateral VWF secretion may be directionally consistent with other associated roles for CLU in angiogenesis, amyloidosis and neointimal hyperplasia, as these processes are more likely to affect the basolateral surface than the plasma surface of ECs." (PMID 38363768, 2024). "Platelets aggregate at vascular amyloid deposits and promote amyloid beta deposition by releasing clusterin to promote amyloid beta fibrillization and adenosine diphosphate (ADP) to enhance platelet activation." (PMID 36734880, 2023). "More importantly, the expression of CLU in astrocytes is sufficient to rescue the impaired synaptic structure and function in CLU knockout mice and attenuates amyloid pathology and synaptic defects in 5XFAD mice." (PMID 38249295, 2023). "Previous mouse studies directly linked platelet-derived factors such as amyloid beta and clusterin with amyloid plaque formation." (PMID 36734880, 2023). "This study was aimed to further elucidate the role of CLU in AD with the focus on physiologic manipulation of expression and the resulting impact on the pathological accumulation of amyloid in the brain." (PMID 33246484, 2020). "Subsequently, we and others have demonstrated that complete CLU deletion using global knockout (Clu−/−) mice in different models of amyloidosis has a profound effect on amyloid aggregation and clearance, resulting in reduced total and fibrillar plaques." (PMID 33246484, 2020). "In particular, we uncovered neuroprotective properties of CLU overexpression, that results in a significant reduction of amyloid pathology and overall improvement of amyloid-related pathological features, including neurotoxicity and gliosis." (PMID 33246484, 2020). "Consistent with previous reports, CLU was highly elevated in AD cases compared to normal controls, an effect partially attributed to the presence of abundant amyloid pathology in AD brains." (PMID 33261653, 2020). "The use of CLU-knockout (KO) animal models of amyloidosis has enabled the study of the relationship between clusterin and Aβ in vivo." (PMID 30872998, 2019). "We discovered, using a differential proteomics approach, that extracellular chaperones such as fibrinogen, clusterin, haptoglobin, alpha-1-anti-trypsin and 2-macroglobulin are overrepresented in transthyretin amyloidosis." (PMID 26147092, 2015). "Some of these chaperones were found overrepresented in several other amyloid diseases, as clusterin in Alzheimer." (PMID 26147092, 2015). "Moreover, our study is the first to show that CLU haploinsufficiency leads to more severe amyloidosis." (PMID 33246484, 2020). "As previously shown, we found an extensive CLU co-localization with amyloid deposits in AD brains." (PMID 33261653, 2020).
amyloid (continued). "Since many amyloid-related proteins including SAA, ApoA-I, ApoA-IV, ApoC-II, ApoE, clusterin, and Aβ are associated with HDL, nutritional treatments modifying the metabolism of HDL might prevent several types of amyloidosis." (PMID 28225824, 2017). "Clusterin (CLU) is a lipoprotein found to be part of amyloid plaques." (PMID 24806343, 2014). "It has been hypothesized that CLU is involved in amyloid clearance, playing a protective role in AD." (PMID 25051234, 2014). "Interestingly, one member of this class, valproate, increases CLU expression in human astrocytes and reduces amyloid accumulation as well as behavioral deficits in mouse amyloid models." (PMID 22506010, 2012). "In support of these findings, the reduction of CLU showed opposite results i.e., substantial increase of amyloid plaque load in both cortex and hippocampus of APP/PS1; Clu+/− mice, and in CAA within the cerebrovasculature of APP/PS1; Clu−/− mice." (PMID 34454574, 2021). "We found that CLU overexpression resulted in a significant reduction of total and fibrillar amyloid in both cortex and hippocampus in the APP/PS1 mouse model of AD amyloidosis." (PMID 33246484, 2020). "We used immunofluorescent (IF) labelling to compare clusterin immunostaining in N3ECD GOM deposits in CADASIL and amyloid deposits in CAA subjects." (PMID 25940137, 2016). "Cross-sectionally, CSF sTREM2, YKL-40, clusterin and fractalkine were higher only in groups with tau pathology, independent of amyloidosis (p < 0.001, A+/T+ or N+ and A−/T+ or N+, compared to A−/T−/N−)." (PMID 38093257, 2023). "In those with tau pathology (T or N+), sTREM2, YKL-40, clusterin, and fractalkine were all significantly higher at baseline, regardless of amyloidosis (A− or A+)." (PMID 38093257, 2023). "However, subsequent work by the same group showed that knocking out both CLU and APOE in PDAPP mice resulted in increased Aβ production and amyloid deposition and earlier onset of AD-pathology than the APOE-KO alone." (PMID 30872998, 2019). "Moreover, in this same study, we demonstrated colocalization of clusterin with Aβ in plaques in the brains of a transgenic mouse model of AD (TASTPM), thus, adding further support to the theory that clusterin may be implicated in amyloid formation and clearance." (PMID 26635716, 2015). "From these observations, an anti-amyloidogenic role of clusterin due to its chaperone function was deduced, but studies on clusterin knockout mice have not provided clear answers on its neuroprotective function and fueled the ongoing controversy about its beneficial role in amyloid diseases." (PMID 31798396, 2019). "CSF sTREM2, YKL-40, clusterin, fractalkine (p < 0.001) and MCP-1 (p < 0.05) were all higher in T or N+, with or without amyloidosis at baseline, but remained stable over time." (PMID 38093257, 2023). "Notably, we also found a significant increase in CLU levels in primary tauopathies with no amyloid pathology, including PiD and CBD compared to controls, indicating CLU upregulation in response to tau aggregation." (PMID 33261653, 2020).
lung carcinoma (27 papers, 2007 to 2026). "A previous study has found an association between CLU and BaP in lung cancers; specifically, the overexpression of CLU was observed in BaP-transformed 16HBE cell line T-16HBE-C1 cells." (PMID 37239129, 2023). "CLU expression has been studied, and it has been found to be linked to tumorigenesis in various types of cancer, such as breast, ovarian, liver, and lung cancer." (PMID 37239129, 2023). "In our current study, it is noteworthy that the downregulation of CLU is closely associated with tumor metastasis, according to the analysis of TCGA lung cancer datasets, as well as the anti-metastatic effect of CLU overexpression both in vitro and in vivo." (PMID 35626071, 2022). "Progranulin (PGRN), endothelial cell-specific molecule-1, clusterin (CLU), and human epididymis protein 4 (HE-4) are novel proteins reported to have diagnostic and prognostic potential in lung cancer." (PMID 36595996, 2022). "Taken together, our data showed that TAK1-NF-κB axis played a critical role mediating growth-promoting effect of CLU-deficient lung cancer cells." (PMID 33052230, 2020). "In case of CLU, its inactivation resulted in hyperactivation of TAK1- NF-κB signaling axis and TAK1 inhibitor exhibited exquisite cytotoxicity to CLU deficient lung cancer cells." (PMID 33052230, 2020). "Taken together, our data showed unique sensitivity of CLU deficient lung cancer cells to TAK1 inhibitors." (PMID 33052230, 2020). "We identified aptamer-associated protein biomarkers for lung cancer such as vimentin, annexin A2, annexin A5, histone 2B, neutrophil defensin, and clusterin." (PMID 26061649, 2015). "CLU gene expression has been linked to an elevated risk of lung cancer." (PMID 36685863, 2022). "Lung cancer cells with loss of function of CLU show exquisite sensitivity to TAK1 inhibitors." (PMID 33052230, 2020). "Our results have shown that TAK1 inhibition may synergize with existing drug to treat CLU deficient lung cancer patients." (PMID 33052230, 2020). "Furthermore, we developed the platform as a distinct tool to discover the diagnostic markers of lung cancer and define the role of Clusterin (CLU), a biochemical molecule contributing to the preferential bacterial chemotaxis towards NCI-H460 over 16HBE." (PMID 29686328, 2018). "Collectively, our study indicated clusterin could influence transdifferentiation from lung squamous cell carcinoma to lung adenocarcinoma, this potentially associated with lung cancer origination and progression." (PMID 28954633, 2017). "Furthermore, our findings extend the current understanding of the kinase activity of ROCK1 without affecting cellular cytoskeleton and identify a novel mechanism underlying ROCK1-mediated ERK phosphorylation and activation due to CLU loss during lung cancer progression." (PMID 35626071, 2022). "As indicated by the DT model, CLU functions as a tumor suppressor in the early stages of carcinogenesis, and has been suggested as a relevant gene in lung cancer." (PMID 41144480, 2025). "In parallel, a wound-healing assay further showed that the wounds of the vector-control H460 cells healed much slower than those of the CLU-silenced H460 cells, consistently supporting the pro-migratory role of silencing CLU in lung cancer cells." (PMID 35626071, 2022). "Meanwhile, the expression of CLU was remarkably diminished in lung cancer bone metastasis loci when compared with subcutaneous tumors in the mouse model and hardly detected in the bone metastasis loci of lung cancer patients when compared with the primary." (PMID 35626071, 2022). "According to other scholars’ studies on the expression and potential role of CLU in lung cancer serum and tissue, their results are inconsistent, demonstrating the instability of CLU expression in serum and tissue samples." (PMID 35291954, 2022).
lung carcinoma (continued). "To investigate the biological function of CLU in lung cancer, we overexpressed exogenous CLU in two lung cancer cell lines, H1975 and H1299, both of which have almost undetectable CLU protein levels." (PMID 35626071, 2022). "The silencing of CLU promotes lung cancer cell migration and invasion, while the overexpression of CLU potently inhibits these phenomena." (PMID 35626071, 2022). "Inhibiting ROCK1 through Y27632 treatment significantly abrogated the pro-invasive and pro-migratory effects of silencing CLU in lung cancer cells." (PMID 35626071, 2022). "To further validate the protein expression levels of CLU in lung cancer tissues, we performed immunohistochemical staining in 10 pairs of paraffin-embedded lung cancer tissues and adjacent normal lung specimens." (PMID 35626071, 2022). "In this study, we demonstrate that precursor CLU is widely downregulated in lung cancer tissue, in which secretory CLU proteins are slightly decreased." (PMID 35626071, 2022). "Knockdown of CLU was verified to significantly promote the growth of lung cancer cells in vitro and in vivo." (PMID 35270630, 2022). "The results showed that protein levels of CLU in lung cancer tissues were dramatically lower than those in paracarcinoma lung tissues." (PMID 35626071, 2022). "Impressively, overexpressing CLU potently inhibits the migration, invasion and metastasis of lung cancer cells, whereas silencing CLU promotes this behavior; however, it appears that secretory CLU fails to exert similar anti-metastatic effects." (PMID 35626071, 2022). "Based on our signaling model, we predicted that CLU protein level reversely correlated with NF-κB signaling activity in lung cancer cells." (PMID 33052230, 2020). "We found comparable CLU mRNA level between tumor samples and most of the lung cancer cell lines, which was consistently lower than that of para-tumoral tissues." (PMID 33052230, 2020). "Experimental Design: Using clinical data, in vitro cell line data and in vivo mouse model data, we revealed the tumor suppressive role of Clusterin in lung cancer." (PMID 33052230, 2020). "We also noticed similar significant correlation in stage I patients, indicating that CLU was a clinically relevant TSG in lung cancer and that CLU played an essential role in early stage of lung cancer development." (PMID 33052230, 2020). "In order to validate its TSG function, we sought to ectopically express CLU in lung cancer cell lines with lower baseline expression and knockdown in those with relatively higher expression." (PMID 33052230, 2020). "We also delineated the signaling cascade elicited by loss of function of CLU in NSCLC cells and tested precision medicine for CLU deficient lung cancers." (PMID 33052230, 2020). "Taken these evidences together, we conclude that CLU is a NSCLC tumor suppressor per se in lung cancer." (PMID 33052230, 2020). "In contrast, clinical data, cell line data, and in vivo data in our current work strongly argue that CLU is a tumor suppressor in lung cancer." (PMID 33052230, 2020). "Analysis using proteomics and verification tests revealed clusterin (CLU) was one of the key biochemical molecules involved in the preferential chemotaxis of E. coli to target lung carcinoma cells." (PMID 29686328, 2018). "In order to detect clusterin’s function in lung cancer differentiation, we confirmed the SP-C and p63 protein and mRNA levels in A549 cell lines." (PMID 28954633, 2017). "To confirm the Clusterin expression in lung cancer, we detect clusterin expression in one lung adenocarcinoma tissue array slide and one lung squamous cell carcinoma tissue array slide (75 pairs each) by IHC assay." (PMID 28954633, 2017). "To further elucidate the significance of clusterin, we detect the level of clusterin in the serum of lung cancer patients." (PMID 28954633, 2017). "This is the first time that clusterin has been shown to modulate lung cancer cell transdifferentiation." (PMID 28954633, 2017).